CXCL8 (C-X-C motif chemokine ligand 8)
Diseases named in the same sentence as CXCL8 in open-access papers (continued):
Sharing a sentence is not in itself a finding about the gene and the disease.
dengue (85 papers, 2007 to 2026). "Low CCL5 and high CXCL8 (IL8) in plasma in initial stages of dengue infection have been studied as predictive markers of severe dengue." (PMID 39284947, 2024). "The increased expression of TNFSF10 and CXCL8 in our patient cohort can be correlated clinically to lymphocyte and neutrophil counts in dengue HVR patients." (PMID 37644081, 2023). "Interaction of platelets isolated from dengue patients with monocytes from healthy individuals lead to the synthesis and secretion of IL-1β, CXCL8, and IL-10 by the monocytes." (PMID 33102253, 2020). "The cytokines IL-1β, CXCL8, and IL-10, released by monocytes in response to interactions with platelets from dengue patients, are frequently observed to be increased in plasma of severe dengue patients." (PMID 33102253, 2020). "CBMCs also produced 212 or 359 pg/mL of CXCL8 following transfection with polyI:C (P = 0.015) or antibody-enhanced dengue virus infection (P = 0.0073), respectively (n = 4–6)." (PMID 22479521, 2012). "Moreover, high serum levels of TNF-α, IL-1β, IL-6, CXCL-8/IL-8, and IL-10 correlated with severity of the disease in dengue patients, showing a preponderant role of NF-kB-dependent inflammatory response in dengue immunopathogenesis." (PMID 40934228, 2025). "Amongst the cytokines and chemokines found elevated in DENV infection, we found C-X-C motif chemokine ligand 8/interleukin-8 (CXCL8/IL-8) in our set of DEGs, reiterating the role of inflammatory mediators in increasing vascular permeability and dengue severity." (PMID 37644081, 2023). "A study has suggested that low levels of CCL5 and high levels of CXCL8 during early dengue infection could serve as a marker for severe dengue disease." (PMID 33102253, 2020). "Among them, a vast panel of increased cytokines and chemokines in severe dengue, such as IFN-γ, GM-CSF, IL-10, CCL4/MIP-1β, IL-1β, CXCL8/IL-8 TNF-α, CXCL10/IP-10, CCL2/MCP-1, and IL-18." (PMID 35631030, 2022). "In our study, higher plasma levels of the proinflammatory cytokines TNF-α, IL-6 and IL-18, and the anti-inflammatory cytokine IL-10 and the chemokines CXCL8/IL-8, CCL2/MCP-1 and CXCL10/IP-10 were found in the dengue patients compared to the healthy controls." (PMID 34578370, 2021). "Patients with severe dengue disease and those with acute Japanese encephalitis exhibited excessively high levels of proinflammatory cytokines, known as a cytokine storm, including GM-CSF, TNF-α, IL-3, IL-6, and IL-8/CXCL8." (PMID 39972499, 2025). "As in our previous studies, the dengue patients had high plasma levels of the cytokines TNF-α (p < 0.001), IL-6 (p = 0.005), IL-10 (p < 0.001) and, IL-18 (p = 0.001) and the chemokines CXCL8/IL-8 (p < 0.001), CCL2/MCP-1 (p < 0.001), CXCL10/IP-10 (p = 0.001) compared to healthy controls." (PMID 34578370, 2021).
malaria (76 papers, 2011 to 2026). Malaria is a serious and sometimes fatal disease caused by a parasite that commonly infects a certain type of mosquito which feeds on humans. "CXCL8 is increased in severe malaria, its expression associated with parasite density and has been consistently identified as a DEG in co-culture studies." (PMID 38033133, 2023). "We show during malaria age is associated with increased inflammatory chemokines CCL2, CCL3, CXCL8, CXCL9, along with CRP, and IDO, which associate with symptoms." (PMID 41027884, 2025). "TGF-β and CXCL8 levels were also significantly higher in coinfections than in malaria monoinfections." (PMID 36716305, 2023). "The meta-analysis results based on the limited number of studies showed that IFN-γ and CXCL8 levels were significantly increased in malaria coinfections compared to malaria monoinfection." (PMID 36716305, 2023). "As presented above, TNF-α, CSF-2, and CXCL8 have been shown to be at increased levels during both malaria and babesiosis." (PMID 36839438, 2023). "Chemokines such as CXCLI and CXCL8 are known neutrophil chemoattractants, were at an increased level in the plasma of severe malaria patients." (PMID 35967409, 2022). "Stimulation with plasma from malaria patients resulted in a significantly increased concentration of CXCL8 in the culture supernatant of ECs." (PMID 34359826, 2021). "Additional cytokines were elevated in malaria cases compared to healthy controls and included IL-1ra, IL-10, IL-8/CXCL8, and macrophage inflammatory protein 1β (MIP-1β)/CCL4." (PMID 28775960, 2017). "Circulating levels of CCL4 (also known as MIP-1β), CXCL10 (also known as IP-10), CXCL4 and CXCL8 have been found to be significantly elevated in CM cases compared with mild malaria cases or healthy control individuals." (PMID 24476686, 2014). "Different from IL-6 and CXCL-8, evidences suggest that exacerbated levels of IFN-γ are directly correlated with the severity of the malaria caused by P. vivax and the more severe the symptoms are the lower levels of IL-10 are produced." (PMID 24741587, 2014). "The importance of IL-6 and CXCL-8 has been shown in malaria, which are produced mostly by monocytes." (PMID 24741587, 2014). "Compared to malaria monoinfection, IFN-γ and CXCL8 levels were significantly increased in malaria coinfections [(P < 0.001, MD: 26.10 pg/mL, 95% CI: −21.81–−10.67 pg/mL, I2: 99.21%, 5 studies) and (P < 0.001, MD: 366.02 pg/mL, 95% CI: 292.1–439.94 pg/mL, I2: 99.80%, 3 studies), respectively]." (PMID 36716305, 2023). "Although higher levels of CXCL-8, another inflammatory biomarker, are found in the circulation of P. vivax-infected patients, the chemotaxis of neutrophils towards this chemokine has been reported to be impaired during malaria." (PMID 24741587, 2014). "No direct correlations were reported between CXCL-8 levels and severity or complications of malaria caused by P. vivax." (PMID 24741587, 2014). "In addition, in vitro differentiated syncytiotrophoblasts have been shown to produce CCL3, CCL4 and CXCL8 in response to stimulation with malaria hemozoin, which is highly abundant in the placenta during PM." (PMID 24476686, 2014). "Distinct cytokine profiles in malaria and filariasis coinfections were IL-1Ra, IL-10, CXCL5, CXCL8, and CXCL10." (PMID 36716305, 2023). "Distinct cytokine profiles in malaria and schistosomiasis coinfections were TNF, IFN-γ, IL-4, IL-5, IL-10, TGF-β, and CXCL8." (PMID 36716305, 2023). "Among the top 50 genes identified in our RNA-Seq experiment, 5 of them (IFNG, CXCL8, IL3RA, SNX10, MYOF, and RSAD2) had promoter regions that were significantly more accessible in convalescent child patients with malaria than in adult convalescent patients." (PMID 35642634, 2022). "For cytokines IL-6, IL-1RA, IL-10 and IL-11 and chemokines CXCL1, CXCL8, CXCL10, CCL3 and CCL2, significantly higher concentrations were found in plasma samples of malaria patients compared to healthy controls." (PMID 34359826, 2021).
malaria (continued). "Stimulation of ECs with plasma from malaria patients resulted in significantly increased levels of IL-11, CXCL5, CXCL8, CXCL10 and VEGF in comparison to stimulation of ECs using plasma from healthy controls." (PMID 34359826, 2021). "Within the malaria pathway, miR-146a suppresses the CD40L, CXCL8, IFNγ, TLR2, TLR4, and ITGβ2 genes." (PMID 29747626, 2018). "Increased levels of CXCL8 and CXCL9 as well as reduced levels of CCL5 (also known as RANTES) have been observed in severe malaria patients." (PMID 24476686, 2014). "Chemokine release is also associated with the malaria blood stage, but HZ alone did not induce the secretion of any of the chemokines investigated, CXCL8 (IL-8), CXCL9, CXCL10, CCL2 and CCL5." (PMID 40717771, 2025). "Interestingly, IL8/CXCL8 is also involved in neutrophil recruitment, which is increasingly being seen as having an important role in malaria pathogenesis." (PMID 38033133, 2023). "Culturing ECs with plasma from malaria patients (27 returning travellers) resulted in significantly increased secretion of IL-11, CXCL5, CXCL8, CXCL10, vascular endothelial growth factor (VEGF) and angiopoietin-like protein 4 (ANGPTL4) if compared to matching controls (22 healthy individuals)." (PMID 34359826, 2021). "In the context of malaria, altered placental cytokine concentrations have been demonstrated in the presence of infection, with increased expression of both pro-inflammatory cytokine (IL-1β and TNF) and chemokines (CXCL8), and decreased expression of IL-6." (PMID 31188820, 2019). "Moreover, cerebrospinal fluid levels of CXCL10, CXCL8 and CCL4 have been found to be significantly higher in children with CM compared with children with SMA and non-malaria-infected individuals." (PMID 24476686, 2014). "The lack of difference in the levels of IL-6 and CXCL-8 according to the number of malaria episodes was expected since they are biomarkers produced by cells from the innate immune system." (PMID 24741587, 2014). "Interestingly, neutrophils from the malaria patients expressed high levels of GRK2, low levels of CXCR2, and displayed impaired chemotaxis towards IL-8 (CXCL8)." (PMID 22745844, 2012). "Moreover, post mortem MIP-1β/CCL4, IL-8/CXCL8, and IP-10/CXCL10 levels were significantly elevated in cerebrospinal fluid (CSF) of fatal P. falciparum-induced CM cases when compared to fatal severe malarial anemia cases and non-malaria deaths." (PMID 28775960, 2017). "In another study, IL-8/CXCL8 was elevated in CSF of non-fatal CM cases of P. falciparum-infected children, while MCP-1/CCL2, MIP-1α/CCL3, MIP-1β/CCL4, and RANTES/CCL5 levels were comparable to malaria-free controls." (PMID 28775960, 2017). "Despite the fact that neutrophils are an important source of cytokines, we found that except for IL-8 (CXCL8), the neutrophils from malaria patients produced none or very small amounts of pro-inflammatory cytokines (i.e., IL-1β, IL-6, and TNF-αin response to TLR agonists." (PMID 22745844, 2012).
osteoarthritis (74 papers, 2008 to 2025). A noninflammatory degenerative joint disease occurring chiefly in older persons, characterized by degeneration of the articular cartilage, hypertrophy of bone at the margins and changes in the synovial membrane. "In osteoarthritis (OA), CXCL8 and CXCL11 affect chondrocyte apoptosis and proliferation through the JAK-STAT and NF-κB signaling pathways." (PMID 41416066, 2025). "Known canonical pathways in RA such as chemoattraction promoted by IL-8/CXCL8 signalling, granulocyte adhesion and diapedesis of immune cells, and high expression of degrading enzymes and growth factors in the osteoarthritis pathway were observed." (PMID 35002734, 2021). "In this study, we identified and validated four differentially expressed genes (CXCL8, CXCL2, DUSP5, and TNFSF11) as promising diagnostic biomarkers for osteoarthritis (OA), which collectively mediate immune regulation, inflammatory responses, and bone remodeling in OA pathogenesis." (PMID 40672822, 2025). "A co-culture of SVF and TMJ-derived synoviocytes that had been exposed to osteoarthritis showed significantly more downregulated inflammatory molecules such as PGE2 and CXCL8/IL-8 compared to a synoviocyte monoculture." (PMID 38391657, 2024). "During the occurrence of osteoarthritis, CXCL8 (C-X-C Motif Chemokine Ligand 8) and TNF-α (Tumor necrosis factor α) can induce the expression of S100A11 and promote its release to the extracellular space to form a dimer." (PMID 34179021, 2021). "Conditioned media from osteoarthritis tissues like cartilage, IFP, meniscus, and synovium induced and enhanced production of CXCL8 and CCL21 in the synoviocyte cell line." (PMID 32189997, 2020). "SHH autocrine treatment of osteoarthritis MSC stimulates proliferation, chondrogenesis, hypertrophy, and replicative senescence with elevated SASP gene expression including IL1B, IL6, CXCL1, and CXCL8." (PMID 34646822, 2021).
cervical carcinoma (73 papers, 2007 to 2026). A carcinoma arising from either the exocervical squamous epithelium or the endocervical glandular epithelium. "While CXCL8, a pro-tumor chemokine, is implicated in cancer progression and treatment resistance across malignancies, its role in cervical cancer radioresistance remains uncharacterized." (PMID 40596054, 2025). "In this study, we identified five ubiquitination-related biomarkers (MMP1, RNF2, TFRC, SPP1, and CXCL8) that are significantly associated with cervical cancer." (PMID 40809844, 2025). "In cervical cancer, high expression of CXCL8 is associated with the inflammatory tumor microenvironment and immune evasion." (PMID 40517358, 2025). "Clinically relevant radioresistant cell models remain scarce, and CXCL8’s role in cervical cancer—despite its tumorigenic/therapy-resistant associations in other cancers—is poorly characterized." (PMID 40596054, 2025). "Intersection analysis revealed 18 genes that were significantly differentially expressed, including the five selected biomarkers (MMP1, RNF2, TFRC, SPP1, and CXCL8), which are significantly associated with cervical cancer progression." (PMID 40809844, 2025). "A bioinformatic study revealed that a signature comprising four genes (RIPOR2, DAAM2, SORBS1, CXCL8) was found to be associated with survival in cervical cancer patients." (PMID 36497200, 2022). "In conclusion, CXCL8 is overexpressed in cervical cancer tissues and cell lines, and is associated with malignant status and prognosis in cervical cancer patients." (PMID 28883082, 2017). "The aim of our study was to explore the status of CXCL8 expression in cervical cancer tissues and cell lines, and analyze the association between CXCL8 expression and clinicopathological characteristics in cervical cancer patients." (PMID 28883082, 2017). "Overall, our study demonstrated that CXCL8 expression was significantly increased in cervical cancer and associated with the malignant status and prognosis in cervical cancer patients." (PMID 28883082, 2017). "mRNA profiling and TCGA-CESC analysis identified CXCL8 as a key radioresistance mediator in cervical cancer via prognostic modeling." (PMID 40596054, 2025). "Cox regression analysis of 96 candidate radiosensitivity regulators prioritized CXCL8 among eight key genes in cervical cancer." (PMID 40596054, 2025). "While CXCL8 is known to promote metastasis in other cancers, our study is the first to demonstrate its necessity for acquired radioresistance in cervical cancer via in vitro and clinical cohort validation." (PMID 40596054, 2025). "In this study, CXCL8 emerged as a critical mediator of radiotherapy resistance in cervical cancer, implicating its role in acquired radioresistance." (PMID 40596054, 2025). "CXCL8 plays a role in modulating immune infiltration, thereby influencing the prognosis of patients with various cancers, particularly cervical cancer." (PMID 40406253, 2025). "Conversely, inhibiting CXCL8 curtails cervical cancer cell proliferation and induces cancer cell apoptosis." (PMID 38275602, 2024). "The inhibition of CXCL8 in combination with miR-302c-3p and/or miR-520a-3p overexpression had proliferation-suppressing and apoptosis-stimulating effects on cervical cancer cells." (PMID 34833360, 2021). "In cervical cancer tissues and cell lines, CXCL8 mRNA and protein expression were increased compared to normal cervical tissues and cervical epithelial cell lines." (PMID 34833360, 2021). "In previous studies, T. vaginalis infection induced the production of inflammatory cytokines such as IL-1β, IL-6, CCL2 and CXCL8 in prostate epithelial cells as well as cervical cancer cells." (PMID 32196489, 2020). "We found that levels of CXCL8 mRNA were increased in cervical cancer cell lines compared with normal cervical epithelial cell lines (P<0.001)." (PMID 28883082, 2017).
cervical carcinoma (continued). "In our study, we observed that CXCL8 was highly expressed in cervical cancer tissues compared with normal cervical tissues in microarray datasets." (PMID 28883082, 2017). "CXCL8 mRNA and protein expressions were increased in cervical cancer tissues and cell lines compared with normal cervical tissues and cervical epithelial cell lines." (PMID 28883082, 2017). "Kaplan–Meier survival analysis indicated that cervical cancer patients with CXCL8 protein’s high expression had shorter overall survival compared in patients with CXCL8 protein low expression (P<0.001)." (PMID 28883082, 2017). "In our study, we observed cervical cancer patients with CXCL8 protein high expression had shorter overall survival compared with patients with CXCL8 protein low expression." (PMID 28883082, 2017). "In conclusion, CXCL8 is highly expressed in cervical cancer tissues and cell lines, and correlated with malignant status and prognosis in cervical cancer patients." (PMID 28883082, 2017). "Meanwhile, multivariate Cox regression analyses suggested that CXCL8 protein’s high expression was an unfavorable independent prognostic factor for cervical cancer patients (P=0.030)." (PMID 28883082, 2017). "In order to confirm the prognostic significance of CXCL8 in cervical cancer patients, we analyzed a cohort that included 246 cervical squamous cell carcinoma and endocervical adenocarcinoma patients from The Cancer Genome Atlas database." (PMID 28883082, 2017). "Immunohistochemical analysis showed that CXCL8 protein expression was increased in cervical cancer tissues (56.5%, 61/108) compared with normal cervical tissues (29.6%, 8/27) (P=0.013)." (PMID 28883082, 2017). "CXCL8 mRNA and protein expressions were also observed in human cervical cancer cell lines (Caski and HeLa) and human normal cervical epithelial cell lines (Ect1/E6E7 and End1/E6E7)." (PMID 28883082, 2017). "We measured the levels of CXCL8 protein expression in 108 cervical cancer samples by using immunohistochemical staining, and analyzed the correlation between the protein expression of CXCL8 and clinicopathological characteristics of cervical cancer." (PMID 28883082, 2017). "Similar to our result, we also found cervical cancer patients with CXCL8 high expression had a shorter survival time that those with CXCL8 low expression (P<0.001)." (PMID 28883082, 2017). "In our study, we found that CXCL8 was highly expressed in cervical cancer tissues compared with normal cervical tissues in microarray datasets (GSE9750 and GSE7803)." (PMID 28883082, 2017). "Compared with adjacent normal cervical tissues, CXCL8 mRNA was highly expressed in cervical cancer tissues (P<0.001)." (PMID 28883082, 2017). "Meanwhile, we measured the levels of CXCL8 protein expression in 108 cervical cancer samples by using immunohistochemical staining, and analyzed the correlation between the protein expression of CXCL8 and clinicopathological characteristics of cervical cancer." (PMID 28883082, 2017). "Meanwhile, Western blot suggested that CXCL8 protein expression was elevated in cervical cancer tissues compared with adjacent normal cervical tissues." (PMID 28883082, 2017). "In order to explore the status of CXCL8 in cervical cancer tissues, we analyzed microarray datasets (GEO accession number: GSE9750 and GSE7803)." (PMID 28883082, 2017). "In vitro, assays of cell viability, clone formation, apoptosis and cell cycle were conducted following transient transfection of cervical cancer radiotherapy-resistant cell strains with knockdown of CXCL8, as well as subsequent addition of exogenous CXCL8 to cervical cancer parental cell strains." (PMID 40596054, 2025). "This suggests that MMP1 may act synergistically with CXCL8 to collectively drive the malignant progression of cervical cancer." (PMID 40809844, 2025). "It is reported that CXCL1, CXCL2, and CXCL8 are related to the tumor growth in cervical cancer." (PMID 36284631, 2022).